IL6 (interleukin 6)
Diseases named in the same sentence as IL6 in open-access papers (continued):
Sharing a sentence is not in itself a finding about the gene and the disease.
diabetes (continued). "The values of evaluated pro-inflammatory cytokines, tumour necrosis factor-α (TNF-α), interleukin-6 (IL-6), and interleukin-1β (IL-1β), assessed from the ascending aorta were elevated by all three cardiovascular risk factors, with the highest levels induced by type 1 diabetes mellitus (up to 259%)." (PMID 35163364, 2022). "Hypertension and diabetes, the most common underlying diseases, were closely related to disease progression in the patients, which could be associated with the level of IL-6." (PMID 33746945, 2021). "According to research, diabetes, hypertension and other diseases can lead to higher IL6 levels in serum, while multiple reports say that genetic polymorphisms of IL6 are closely related to insulin levels and large blood vessels, and may regulate insulin secretion through pancreatic α cells." (PMID 34692849, 2021). "Many studies show that IL-6 gene promoter polymorphism (rs1800795G > C) is associated with the risk for developing both neoplastic and non-neoplastic diseases, including Kaposi sarcoma, intracranial hemorrhage, diabetes mellitus, osteoporosis, and Crohn’s disease." (PMID 32046104, 2020). "In addition, numerous observational studies have found increased levels of the mediators of inflammation, such as C-reactive protein, interleukin-6 (IL-6), and plasminogen activator inhibitor 1, to name only a few, as major associative findings between diabetes and atherosclerosis." (PMID 33330454, 2020). "Interleukin (IL)-6 is a pleiotropic cytokine that is associated with several immunoinflammatory and autoimmune diseases such as systemic lupus erythematous, rheumatoid arthritis and diabetes and is produced by a variety of different cell types with complex, cell-specific mechanisms." (PMID 30974824, 2019). "Besides, diabetes could aggravate bone loss through promoting NF-κB activation and IL-6 and TNF-α release." (PMID 30459613, 2018). "High glucose upregulated the expression of multiple inflammatory cytokines, including tumor necrosis factor-α (TNF-α), interleukin-1β (IL-1β) and interleukin-6 (IL-6), which might be linked to the pathogenesis of the complications of central nervous system in diabetes." (PMID 29867440, 2018). "Furthermore, adipokines and cytokines [tumor necrosis factor-α (TNF-α), interleukin-6 (IL-6), and transforming growth factor-β], induced by fat tissues in obese individuals, trigger a metabolic imbalance (IR, type 2 diabetes mellitus, etc.)by causing subclinical systemic inflammation." (PMID 28008865, 2017). "This is an interesting result since cytokines such as IL-6 are considered as the main regulators of inflammation during diabetic pathogenesis, and only a few compounds have displayed similar or better ameliorative effect of reducing diabetes associated complications than metformin." (PMID 28933769, 2017). "IL-6 may also causes an increased susceptibility to diabetes mellitus." (PMID 28969616, 2017). "On the other hand, a high level of IL-6 by C allele may be dominant in tumor-promoting effects, deteriorate the chronic inflammatory state in diabetes, and synergically increase breast cancer risk, implying that the contribution to breast cancer by diabetes may be varied by different IL-6 levels." (PMID 28591216, 2017). "Treatment of patients with diabetes and periodontal disease with topical melatonin was associated with a significant improvement in the gingival index and in pocket depth, and a statistically significant reduction in concentrations of IL-1β, IL-6 and PGE2 in gingival crevicular fluid." (PMID 29075409, 2017). "Inverse correlation of VO2max with IL-6 and hsCRP in healthy men and with hsCRP, white blood cell count and fibrinogen in men with T2D suggest that lower VO2max might predispose to the development of cardiovascular disease in diabetes." (PMID 27053136, 2016).
diabetes (continued). "General linear model analysis showed that rs28362491 was associated with IL-6 levels by analyses of a dominant model (P<0.001) and a recessive model (P<0.001), and the difference remained significant after adjustment for age, sex, smoking, BMI, hypertension, diabetes, glucose, TG, TC, HDL, and LDL." (PMID 26075620, 2015). "We also aimed to demonstrate whether there was any additional risk besides mortality associated with the presence of comorbidities; only the IL6 rs2069869 GG genotype was associated with mortality risk in patients with diabetes in the pA/H1N1 group (p = 0.011; OR = 40.8, 95% CI: 2.31–720.24)." (PMID 26657940, 2015). "Furthermore, overproduction of TNF-α and IL-6 in pancreas could cause islet dysfunction and accelerate the progression of diabetes." (PMID 24669227, 2014). "Across multiethnic cohorts and meta‐analyses, IL‐6 remains an independent predictor of incident stroke in diabetes; adding IL‐6 to clinical models yields small but reproducible improvements in risk prediction, supporting its use in multimarker panels." (PMID 41567175, 2026). "Hyperglycemia and excess free fatty acids in diabetes activate innate immune pathways, leading to increased levels of circulating cytokines (IL‐6, tumor necrosis factor‐α) and acute‐phase reactants." (PMID 41567175, 2026). "Using LASSO feature selection followed by multivariable logistic regression, a diagnostic nomogram was developed incorporating TLR2, IL-6, TNF-α, ESR, age, and diabetes duration." (PMID 41788768, 2026). "STZ-induced diabetes was associated with a significant decrease in the anti- inflammatory cytokine IL-10 and an increase in the proinflammatory cytokines CXCL-1, IFN-γ, IL-6, IL-18, and IL-33." (PMID 40649891, 2025). "Multivariate analysis identified diabetes, elevated IL-6, and dysbiosis as independent predictors of adverse outcomes." (PMID 39857688, 2025). "In the final model with all predictors, VIF’s were the following: age = 1.25, sex = 1.01, hypertension or CVD = 1.17, diabetes = 1.10, cancer = 1.03, IL-6 = 1.25, TNFR1 = 1.49." (PMID 41280118, 2025). "The positive association between diabetes and IL-10 was mediated 14.7% by TNFR1, 8.1% by IL-6, and 13.1% by TNF-α independently." (PMID 41280118, 2025). "Despite this evidence, the relationship between IL-6 and glycemic control in diabetes remains poorly defined." (PMID 41010714, 2025). "In patients with diabetes and prolonged hyperglycemia, abnormal levels of serum biomarkers of inflammation and oxidative stress including NF-κB and IL-6 are evident together with aberrant free fatty acid (FFA) metabolism." (PMID 41416065, 2025). "In the GSE7014 dataset, the expression of ESR1 was significantly increased, and the expression of IL6 was significantly reduced in diabetes patients." (PMID 40508014, 2025). "The evaluation of markers, such as interleukin-1, IL-6, CRP and TNF-α, is essential for investigating the association between periodontitis and diabetes mellitus." (PMID 40667952, 2025). "ILs are the key contributors to retinal pathology in diabetes—in our previous study, we identified IL-6 and IL-1β as important mediators in DR progression." (PMID 40671907, 2025). "Visceral fat can release large amounts of IL‐6 and is more correlated with diabetes than total body fat." (PMID 39764565, 2025). "Diabetes will be analyzed as a dichotomous variable, while IL-6/GP130/JAK/STAT3 activation will be treated as a continuous variable." (PMID 41397158, 2025). "The positive association between diabetes and GDF15 was mediated 8.0% by TNFR1 and 1.3% by IL-6 independently." (PMID 41280118, 2025). "Persistent IL-6 elevation in PCC has been observed in patients with comorbidities such as diabetes and hypertension, contributing to a chronic low-grade inflammatory state." (PMID 40429727, 2025).
diabetes (continued). "The GSE7014 dataset analysis revealed a significant increase in ESR1 expression and a decrease in IL6 expression in diabetes patients, suggesting their potential roles in metabolic dysregulation and inflammation." (PMID 40508014, 2025). "Individuals with elevated suPAR or elevated IL‐6, in comparison to those with low suPAR or low IL‐6, respectively, were older, had a longer duration of diabetes, higher systolic blood pressure, worse kidney function, and used more medications." (PMID 40619914, 2025). "This process is distinct from other diabetes-related problems, such as retinopathy and nephropathy, in which interleukin-6 (IL-6) and C-reactive protein (CRP) play a more prominent role." (PMID 40149566, 2025). "Pro-inflammatory cytokines, such as tumor necrosis factor-alpha (TNF-α), interleukin-6 (IL-6), and interleukin-1β (IL-1β), are upregulated in individuals with diabetes, contributing to insulin receptor desensitization and impaired glucose uptake." (PMID 40563357, 2025). "Poorly controlled diabetes (HbA1c ≥ 7%) was associated with higher levels of inflammatory markers such as CRP, IL-6, and ferritin, as well as elevated composite indices (NLR, SII)." (PMID 40299484, 2025). "Paradoxically, however, our study results indicated that the increased levels of KRT8 in individuals with diabetes and COVID‐19 correlated with higher levels of IL‐6." (PMID 40476695, 2025). "Our study reinforced the association between the TyG index and biochemical markers commonly associated with diabetes, such as HbA1c, fasting insulin, HOMA-IR, eGFR, WBC, hs-CRP, IL-6, and liver function markers, which is consistent with previous studies." (PMID 40065340, 2025). "The positive association between diabetes and risk of hospitalization or death was mediated 26.7% by TNFR1, 8.3% by IL-6, and 81.6% by GDF15." (PMID 41280118, 2025). "The pathophysiology of diabetes mellitus resembles a state of chronic inflammation, with elevated levels of inflammatory cytokines such as interleukin-6 (IL-6) and tumor necrosis factor-α (TNF-α) in patients with type 2 diabetes." (PMID 40002398, 2025). "Zechner et al12 showed that diabetes increased plasma interleukin 6 concentration and decreased lymphocyte levels during acute pancreatitis." (PMID 41340386, 2025). "Increased levels of CRP and IL-6 are present in all diabetes subtypes compared to their control groups." (PMID 40022072, 2025). "IL-6 stimulates the inflammatory processes in many diseases, such as multiple sclerosis, diabetes mellitus, and atherosclerosis." (PMID 40217768, 2025). "The chronic low-grade inflammation in diabetes promotes the release of inflammatory mediators such as IL-6 and TNF-α, which not only worsen endothelial cell damage but also increase blood vessel permeability and impede angiogenesis." (PMID 40620799, 2025). "In linear regression analysis, including both BMI and diabetes status as confounding variables, the positive association between CRP and IL-6 levels remained significant (p = 2.3e−4 and p = 0.03, respectively)." (PMID 40045464, 2025). "The expressions of IL17A, ACE, TLR4, and IL6 are up-regulated with diabetes that promote the progression of gangrene, whereas the expressions of FGF2 and IGF1 are down-regulated." (PMID 40657379, 2025). "Hyperglycemia further aggravates this process by significantly upregulating pro-inflammatory cytokines such as NF-κB-p65, IL-1β, and IL-6, thus reinforcing chronic inflammation and contributing to diabetes-related pathologies." (PMID 41142063, 2025). "A multiple logistic regression analysis revealed that diabetes, BMI, serum IL-6 level 3 days post-op, and serum TNF-α level 3 days post-op are optimal indicators for predicting LFCN injury in patients undergoing DAA total hip arthroplasty." (PMID 40236989, 2025). "Diabetes increased renal cortical expression of IL-6 and phosphorylated STAT3, which was inhibited by NaHS." (PMID 39782685, 2025).
diabetes (continued). "Inflammatory factors such as IL-6 can impair the functionality of islet cells, thereby accelerating the progression of diabetes." (PMID 41373699, 2025). "There was a significant increase in interleukin-6 (IL-6) levels following the onset of diabetes, indicating a relatively severe inflammatory response." (PMID 41373699, 2025). "We found that a higher eGFR was still significantly associated with higher SCP-PD (C), DCP-PD (C) and was significantly correlated with younger age, lower BMI, lower TG, lower HbA1c, lower interleukin-6 (IL-6), shorter diabetes duration (all p < 0.05)." (PMID 41291794, 2025). "In previous studies of CHF and diabetes patients, depressive symptoms were associated with higher levels of the proinflammatory cytokines TNF‐α, IL‐6, and CRP, and lower levels of the anti‐inflammatory cytokines IL‐10 and ADPN." (PMID 40700022, 2025). "Patients with type 2 diabetes mellitus have higher plasma concentrations of pro-inflammatory cytokines, including IL-1β, IL-6, IL-8, IL-17, IL-18, TNF-α, IFN-γ, and TGF-β, according to research (T2DM)." (PMID 40149566, 2025). "This means that the development of atherosclerosis in individuals with diabetes is contributed to by inflammatory factors, including IL-6." (PMID 41150802, 2025). "Our work supports previous researchers’ findings, which indicate that the length and severity of the diabetes condition are correlated with a linear upward expression of IL-6." (PMID 41150807, 2025). "IL-6 has become an attractive focus in diabetes research due to its multiple functions in regulating glucose balance." (PMID 40003909, 2025). "IL-6 concentrations were significantly elevated in individuals with diabetes and atherosclerosis (1.7 ± 0.5 ng/mL) compared to those without, supporting its role as a pro-inflammatory marker in vascular damage." (PMID 41150802, 2025). "Diabetes has been linked to elevated levels of plasma TNF, IL-1b, interleukin 6 (IL-6), interferon-g (IFNg), and PAI-1, as well as changes in immune cell responses, resulting in chronic low-grade inflammation." (PMID 40283013, 2025). "Looking forward, the clinical application of IL-6 measurement in diabetes management requires further exploration." (PMID 41010714, 2025). "Individuals with simultaneously elevated suPAR and IL‐6 (n = 109) were the oldest, with the highest body mass index, the longest duration of diabetes, worst kidney function, highest HbA1c, frequent smokers, and used most medication." (PMID 40619914, 2025). "Key targets such as JUN, AKT1, ESR1, CASP3, TNF, SRC, and IL6 were identified as central regulators in diabetes-related pathways, with molecular docking confirming strong binding interactions between Chaga-derived phytochemicals and these targets." (PMID 40508014, 2025). "Although IL-6 has been studied in both type 1 (T1D) and type 2 diabetes (T2D), its relationship with glycemic control across diabetes subtypes remains unexplored." (PMID 41010714, 2025). "IL-6 and monomeric CRP, two of the most commonly assayed inflammatory biomarkers, are used to refine diabetes risk prediction." (PMID 41302503, 2025). "In particular, elevated circulating inflammatory markers such as C-reactive protein (CRP) and interleukin-6 (IL-6) predict the development of type 2 diabetes mellitus." (PMID 39852208, 2025). "In the current study, we found that diabetes impaired macrophage lipid metabolism during liver IR and caused more severe aseptic inflammation (TNF‐α, IL‐1β, IL‐6, and IL‐18)." (PMID 40778489, 2025). "Among the markers analyzed, CRP demonstrated the strongest predictive value for diabetes, followed by IL-6." (PMID 41523554, 2025). "The altered levels of adipokines such as adiponectin and leptin, along with pro-inflammatory markers like CRP and IL-6, underscore the complexity of diabetes etiology in this population." (PMID 41523554, 2025).
diabetes (continued). "Among these, seven key targets (JUN, AKT1, ESR1, CASP33, TNF, SRC, and IL6) were found to have the highest network connectivity, indicating their central role in treating diabetes with Chaga." (PMID 40508014, 2025). "In a large, bi-ethnic US-based cohort, higher IL-6 predicted higher risks of incident diabetes and metabolic syndrome after 9.5 years of follow-up." (PMID 40606939, 2025). "Studies have shown that taurine reduces levels of TNF‐α and IL‐6, both of which play key roles in the pathology of diabetes and cellular senescence." (PMID 40458841, 2025). "IL-6 and TNF-α have been implicated in the increased risk of developing type 2 diabetes mellitus and atherosclerosis and exhibit an inverse relationship with adiponectin levels." (PMID 39857920, 2025). "In parallel, an anti-inflammatory effect of inulin administration on DPN in diverse stages of diabetes was unveiled in this study by reducing pro-inflammatory LPS, IL-6, TNF-α and IL-17A and elevating anti-inflammatory IL-10." (PMID 41264657, 2025). "Interleukin-6, D-dimer, diabetes mellitus, parenchymal hemorrhage, and excessive PEEP were significantly different in the training group when compared to baseline data (p < 0.05)." (PMID 40144625, 2025). "Pro-inflammatory cytokines, such as interleukin-1 beta (IL-1β), tumour necrosis factor-alpha (TNF-α) and interleukin-6 (IL-6), are elevated in patients with diabetes and have been shown to alter glucose metabolism through various signalling pathways." (PMID 40227199, 2025). "For example, chronic physical illnesses (eg, diabetes) can activate proinflammatory cytokines (eg, interleukin-6, tumor necrosis factor alpha), affecting blood-brain barrier permeability and leading to neuroinflammation." (PMID 40611696, 2025). "In the final model with all predictors, VIF’s were the following: age = 1.22, sex = 1.04, hypertension or CVD = 1.18, diabetes = 1.26, cancer = 1.01, IL-6 = 1.27, TNFR1 = 1.99, IL-1b = 1.04, TNF-a = 1.55, IL-10 = 1.11, GDF15 = 2.16." (PMID 41280118, 2025). "It was previously indicated that the levels of proinflammatory cytokines, including TNF-α, IL-1β, and IL-6, are increased as diabetes progresses." (PMID 40589410, 2025). "In comparison with normal controls, STZ-induced diabetes participants showed higher amounts of IL-6 mRNA in the sciatic nerve and DRG." (PMID 39061964, 2024). "In cardiometabolic disorders such as atherosclerosis and diabetes, the progression of complications that result from pro-inflammatory and autoimmune mechanisms is significantly influenced by the presence of IL-6." (PMID 39335642, 2024). "In accordance with previous findings, diabetes has led to a significant increase in IL6 concentration in serum and TLR4 gene expression in cecal tissue samples." (PMID 38626052, 2024). "HCV-seronegative PWID exhibited significantly increased levels of inflammatory biomarkers including soluble (s) TNF-RII, IL-6, sCD14 and sCD163 and the diabetes index HbA1c as compared to community controls." (PMID 38420130, 2024). "The other characteristics were renal colic, diabetes, hemoglobin, IL-6, urine bacterial count, globulin and G/A." (PMID 38896174, 2024). "Many of the cytokines dysregulated in periodontitis, such as IL-6, TNF-α, and IL-17A, play pathogenic roles in conditions like cardiovascular disease, rheumatoid arthritis, diabetes, stress, and certain cancers." (PMID 38891939, 2024). "Patients with metabolic and cardiovascular comorbidities had the highest IL-6 levels, particularly with diabetes and hypertension (98.6 pg/mL) or cardiovascular disease (119.3 pg/mL)." (PMID 39469275, 2024). "Plasma levels of IL‐6 predicted the incidence of neuropathy over 5 years in Chinese diabetes patients." (PMID 37795833, 2024). "For example, the IL-6 levels are measured to determine the correlation between PD and systemic diseases, such as diabetes, atrial fibrillation (AF), heart disease and oral cancer, as well as other factors such as smoking and obesity." (PMID 38396821, 2024).